PTER (phosphotriesterase related)
Description:
N-acetyltaurine hydrolase that regulates feeding by catalyzing the hydrolysis of N-acetyltaurine into taurine and acetate. N-acetyltaurine has anorexigenic and anti-obesity effects that are dependent on GFRAL receptor and GDF15 (By similarity). PTER also acts on other N-acetyl amino acids (Met, Ile, Leu, Val) and N-propionyltaurine, but at lower rates (By similarity).
Synonyms: HPHRP; RPR-1
Tractability: PROTAC: ubiquitination databases record sites on it; its protein half-life has been measured.
Gene: Protein-coding gene on chromosome 10 (16,436,940 to 16,515,220, forward strand). Ensembl gene ENSG00000165983.
Subcellular location: Cytoplasm, cytosol
Subcellular location (Human Protein Atlas): Nucleoplasm; Cytosol
Gene Ontology:
Molecular function: N-acetyltaurine hydrolase activity; protein binding; aminoacylase activity; hydrolase activity, acting on ester bonds; zinc ion binding
Biological process: epithelial cell differentiation; taurine metabolic process; regulation of appetite
Cellular component: extracellular exosome; cytosol
Genetic constraint (gnomAD): Loss-of-function variants: 34 observed, 29.13 expected, observed/expected ratio (o/e) 1.17, 90% interval 0.89 to 1.55. The upper end of that interval is the gene's LOEUF score, 1.55, which puts it in group 6 of 6, group 1 being the genes least tolerant of losing a copy. Missense variants: 462 observed, 436.12 expected, observed/expected ratio (o/e) 1.06, 90% interval 0.98 to 1.14. Synonymous variants: 167 observed, 159.01 expected, observed/expected ratio (o/e) 1.05, 90% interval 0.93 to 1.19.
Homologues: Orthologues: chimpanzee PTER (99% identical), macaque PTER (93% identical), dog PTER (89% identical), pig PTER (89% identical), mouse Pter (88% identical), rat Pter (87% identical), rabbit PTER (86% identical), guinea pig PTER (83% identical), tropical clawed frog pter (75% identical), zebrafish pter (69% identical), Drosophila melanogaster CG18473 (46% identical).
Diseases named in the same sentence as PTER in open-access papers:
PTER is named in the same sentence as 14 diseases in open-access papers, as found by Europe PMC text mining. Sharing a sentence is not in itself a finding about the gene and the disease. The quoted sentences say what the papers report.
Obesity (8 papers, 2010 to 2024). Accumulation of substantial excess body fat. "We conclude that PTER is expressed in the brainstem and that the full anorexigenic and anti-obesity effects of N-acetyltaurine require functional GFRAL receptors." (PMID 39112712, 2024). "Of interest are the variants in/near five genes (PTER, NPC1, MAF, SDCCAG8 and TNKS/MSRA) that had previously been associated with obesity also using samples of individuals who were extremely overweight." (PMID 21935397, 2011). "Notably, obesity alone, at least in mice, showed a subtle PTER-dependent effect, which underscored the complex gene-by-environment interaction of the Pter locus, taurine levels and diet." (PMID 39112712, 2024). "The results demonstrated that genetic variation in KCNJ11, BDNF, PFKP, PTER and SEC16B were associated with SGA and support the concept that genetic factors associated with obesity and/or type 2 diabetes are more prevalent in those born SGA compared to those born AGA." (PMID 20712903, 2010). "Other obesity susceptibility variants in/near MAF, NPC1, PRL, and PTER have been identified in other GWA studies of early-onset and severe obesity, and putative associations with early life weight gain may be more expected with those variants." (PMID 20520848, 2010). "Nine loci have been associated with extreme obesity at the genome-wide level, five of them influencing BMI / waist circumference as well as risk for extreme obesity (FTO, MC4R, TMEM18, MSRA, NPC1), four loci being more specific of genetic risk for extreme obesity (MAF, PTER, PRL, SDCCAG8)." (PMID 22043164, 2011). "We have found associations (with p values less than 0.05) for SGA with the diabetes related SNP in KCNJ11 and the obesity related SNPs in FTO, PFKP, PTER, SEC16B and BDNF." (PMID 20712903, 2010).
cystic kidneys (1 paper, 2014). "PTER had been reported its expression in the kidney proximal tubular cells, and showed abnormal expression in injured and cystic kidneys." (PMID 24750591, 2014). "From the differential cDNA library screening in between normal and cystic kidneys of the C57BL/6 J-cpk mouse, PTER was significantly under-expressed in cystic kidneys." (PMID 24750591, 2014).
uterine cancer (1 paper, 2014). Primary or metastatic malignant neoplasm involving the uterine corpus and/or the cervix. "In addition, most (if not all) the other ligands are estrogenic in nature, and could thus act as positive factors for ER-dependent breast, ovary and uterine cancers, whereas PTER-ITC is anti-estrogenic at the dose used for this study." (PMID 25119466, 2014).
kidney diseases (1 paper, 2014). "Taken together, these results suggest PTER may also be involved in some kidney diseases, including MN." (PMID 24750591, 2014).
PTER also shares sentences with these, for which no sentence is quoted: diabetes (2 papers); allergic rhinitis (1); bacterial meningitis (1); breast carcinoma (1); cancer (1); COVID-19 (1); hepatitis B (1); liver diseases (1); membranous nephropathy (1); type 2 diabetes (1).